CD86 (CD86 molecule)
Diseases named in the same sentence as CD86 in open-access papers (continued):
Sharing a sentence is not in itself a finding about the gene and the disease.
tumor (continued). "Deeper phenotyping revealed that loss of CD8+ T cells resulted in depletion of classical monocyte Ly6Chi CX3CR1− or CD86+ subsets in both in WT and IFNγRKO tumours, but did not affect F4/80+ macrophage populations." (PMID 39746898, 2025). "In addition, aPD-1@PMPNs promoted the activation of DCs in both tumor-draining and non-tumor-draining lymph nodes, as demonstrated by the increased CD80+CD86+ double-positive population." (PMID 40625885, 2025). "Moreover, further immunostained tumor tissues of lung metastasis nodules showed that treatment with NaHS led to a decrease in CD206 and an increase in CD86 in the GRP78‐WT group, but this effect was abrogated in the GRP78‐C420A group." (PMID 39755930, 2025). "Furthermore, according to IHC staining results, we observed a significant increase in the expression of CD86 (an M1 macrophage marker) and CD8 (a CTL marker) in the tumour tissue of the combination treatment group." (PMID 40830825, 2025). "We investigated macrophage activation in spleen and tumor tissue via CD80 and CD86 expression." (PMID 41583493, 2025). "Another modified adenovirus, LOAd 703, which encodes CD40L and 4-1BBL, has been shown to enhance cytotoxic T cell activity and inhibit tumor progression in a multiple myeloma xenograft model; it also increases tumor immunogenicity by upregulating costimulatory markers CD80 and CD86." (PMID 41294877, 2025). "Thus, CD80 and CD86 are critical for CD4 T cells and for radiation-mediated Treg expansion in the tumor immune environment." (PMID 41417245, 2025). "However, the combination of two SNPs, namely rs1129055 of CD86 gene and rs231775 of the CTLA4 gene caught our attention because CD86 and CTLA4 engage in a receptor-ligand interaction that inhibit anti-tumor immune response." (PMID 41469691, 2025). "Based on functional differences, TAMs can be divided into two phenotypes: M1-type TAMs (marked by CD86, iNOS, and CD169), which secrete pro-inflammatory cytokines to enhance anti-tumor immunity; and M2-type TAMs (marked by CD206, CD163, and CD204), which promote tumor invasion and immune evasion." (PMID 41320762, 2025). "Moreover, using IF, we determined the specific topography of CD20+ tumor cells (intra-T area) and of CD68+CD86+ M1 and CD68+CSF1-R+ M2 macrophages (peri-T area) in DLBCL samples." (PMID 41415285, 2025). "Flow cytometry analysis revealed significant increases in CD80+CD86+ DCs, CD8+CD3+ T cells, and CD44+CD62L‐TEM cells, indicating that FABP5 inhibition effectively enhanced immune responses in the tumor microenvironment." (PMID 40956367, 2025). "Among the population of CD68+ cells, CD206+CD68+ (M2) and CD86+CD68+ (M1) cells accounted for 36.2% and 12.7%, respectively, of the population in tumor-surrounding tissues, whereas they accounted for 13.2% (M2) and 45.3% (M1) of the population in normal tissues." (PMID 41354740, 2025). "Enhanced systemic immunity was evidenced by elevated CD80+CD86+ mature DC populations in tumor-draining lymph nodes and a maximal M1/M2 ratio (41.8% iNOS+CD206− cells) within SINM + US tumors, indicating durable tumor immune microenvironment (TIME) remodeling." (PMID 40892295, 2025). "At present, we do not know the molecular mechanisms that drive CD80 and CD86 signaling in macrophages in the tumor." (PMID 41417245, 2025). "Similarly, in NSCLC, CAR T-cell therapy is being developed to target tumor-specific antigens, such as GPC3, PD-L1, and CD80/CD86, aiming to bypass resistance mechanisms and improve patient outcomes." (PMID 40094890, 2025). "Furthermore, our in vitro and in vivo results demonstrated that TZ‐dSA3‐12 strongly induced the surface expression of CD80 and CD86 on DCs within the tumor microenvironment, and boosted the production of IFN‐γ and GzmB by tumor‐infiltrating CD8+ T cells." (PMID 40492586, 2025).
tumor (continued). "Finally, analyzing the interactions between myeloid cells and tumor cells, we found that high expression of CD80 and CD86 in dendritic cells promoted immune responses or inhibited immune evasion." (PMID 40104502, 2025). "Therefore, we investigated Bcl-2 expression in CD68+CD86+ M1 macrophages in DLBCL samples (intra-T vs peri-T) and in DLBCL vs non-tumor control lymph node samples." (PMID 41415285, 2025). "Furthermore, we confirmed the presence of CD86+ (M1) and CD163+ (M2) macrophages in the tumor microenvironment by using immunofluorescence analysis on frozen tumor sections derived from SeAx/MyLa cell xenografts in the CAM of chicken embryos." (PMID 41221277, 2025). "Interestingly, in vitro silencing of MSLN resulted in a transition from the immune-suppressive TME (Tregs and CD206 + TAM) to the tumor suppressive one (CD8 + T-cells and CD86 + TAM), suggesting the MSLN functional involvement in this process." (PMID 41335396, 2025). "Additionally, preS1‐pHLIP NMs treatment recruited significant numbers of CD3+CD8+ T cells, CD49B+ NK cells, F4/80+CD86+ M1‐polarized macrophages, CD80+CD86+ DC cells and CD11B+Ly6G+ neutrophils into the tumor tissue." (PMID 40091501, 2025). "The tumor-infiltrating cDC1 and cDC2 displayed a migratory and activated phenotype shown by CD40 and CCR7 expression, the RNA-seq data revealed overall upregulation of Cd40, Cd86 but also the cytokine Il12 in BRAFi-sensitive tumors." (PMID 38631706, 2024). "Importantly, RT-induced CTL priming supported by CD86 blockade allowed for reversal of the Treg/CTL ratio, whereas PD-1 blockade likely improved CTL quality, thereby enhancing tumor control." (PMID 38349740, 2024). "We found that both CD80 and CD86 were expressed in the majority of tumor cells, but not in the epidermis, apocrine glands or endothelial cells." (PMID 39619201, 2024). "One mechanism, by which the tumor cells escape the host’s immune response is the hijacking of immune-checkpoints, like programmed cell death ligand 1 (PD-L1), CD80, CD86 and their respective receptors, programmed death receptor 1 (PD-1) and cytotoxic T-cells associated protein 4 (CTLA-4)." (PMID 38962703, 2024). "Further, we confirmed the results by flow cytometry, and the increased percentage of CD86+F4/80+ cells in CD11b+CD45+ cells and decreased percentage of CD206+F4/80+ cells in CD11b+CD45+ cells were observed in A2-APM group in GL261 and G422 tumor mice." (PMID 38320994, 2024). "With a higher affinity for the ligands CD80 and CD86 on antigen-presenting cells (APCs) than the co-stimulation receptor CD28 on T cells, the interaction between CTLA4 and its ligands suppresses T-cell activity, thereby promoting tumor growth." (PMID 39198311, 2024). "Our previous studies revealed that NK cells could promote the maturation of MDSCs from tumor-bearing mice through NK cell-derived IFN-γ, as evidenced by significantly increased expression levels of MHC II and CD86." (PMID 38791188, 2024). "Type 1-polarized macrophages (M1), identified by the expression of CD80, CD86, MHC II, iNOS, and CD68, were phagocytic and could impede tumor progression." (PMID 39434887, 2024). "For example, we observed significantly a lower percentage of I-A/I-E expressing cells, a higher frequency of CD80 expressing cells without any change in the proportion of CD86 expressing cells among Dectin-1+ myeloid cells in the spleen of B16 tumour model." (PMID 38668817, 2024). "TAMs can be further classified into subsets based on surface markers such as M1-TAMs (CD86+CD206−), which may mediate proinflammatory and anti-tumor responses, and M2-TAMs (CD206+), which are thought to be immunosuppressive and promote tumor growth." (PMID 39055715, 2024). "Interestingly, we observed marked upregulation of a series of immune checkpoints (e.g., CD86, CD80, HAVCR2 and LGALS9) in most tumor infiltrating myeloid cells, and a unique pattern in TAMs (e.g., NECTIN2, TNFRSF14, CD276 and TNFRSF9)." (PMID 38414027, 2024).
tumor (continued). "The inhibitory receptors expressed on T cells, interacting with their corresponding ligands expressed on antigen-presenting cells or tumor cells, such as PD-1/PD-L1, CTLA-4/CD86, TIM-3/Galectin-9, TIGIT/CD155, and BTLA/HVEM, play important roles in regulating T cell functions." (PMID 39329729, 2024). "Consequently, our study seeks to evaluate the impact of anti-CTLA4/NKG2A aptamers on immune checkpoint interactions, specifically examining CTLA4-CD80/CD86 and NKG2A-HLA-E interactions between CD8 T cells/NK cells and tumor cells." (PMID 38473398, 2024). "Assuming similar roles of CD80 and CD86 in CCH, their expression patterns as observed in our study therefore seem to strengthen the hypothesis according to which CCH tumor cells gradually adopt the phenotype of mature APCs." (PMID 39619201, 2024). "In cSCC, PD-1, PD-L1, and CD86 showed a significant increase of expression within the invasive front as compared to the tumor core, in contrast to CD28, which did not." (PMID 39329753, 2024). "Moreover, the NicheNetR analysis revealed the potential ligands expressed by C3–4 of LN tumor cells that drive exhausted signatures of CD8 TDYS in RR TFHL, including IL21, TNF, TGFB1, CD80, and CD86." (PMID 38012392, 2024). "To determine whether both Ox-Hcs promote M1/M2 polarization of macrophages in the tumor tissue, we used FACS to measure the distribution of F4/80+CD86+ (M1) and F4/80+CD206+ (M2) in a single-cell suspension, prepared from a tumor." (PMID 39452870, 2024). "Similarly, Exo702 derived from PAN02 cells upregulated CD86 and IFN-γ in bone marrow-derived DCs in a bilateral PAN02 subcutaneous tumor model." (PMID 39499326, 2024). "The NP‐G/P+H‐treated tumor cells significantly enhanced the surface expression of maturation markers on DCs (CD80+CD86+) by 3.86, 3.27, and 1.17 folds compared with PBS, NP‐G/P, and HIFU‐treated tumor cells, respectively, indicating HIFU can promote tumor cell ferroptosis‐triggered DC maturation." (PMID 38342612, 2024). "Therefore, in the context of cancer, the binding of CD86 to CD28 on T lymphocytes can assist in their activation, enhancing an effective anti-tumor immune response." (PMID 38791312, 2024). "According to our in situ hybridization data, CD86 was constantly expressed by CCH tumor cells independent of tumor area or stage of regression, which was recently confirmed on the protein level." (PMID 39619201, 2024). "CTLA-4 inhibition by monoclonal antibodies may induce tumor rejection through direct blockade of CTLA-4 competition for CD-80 (B7-1) and CD-86 (B7-2) ligands, which enhances CD28 co-stimulation." (PMID 39091917, 2024). "APC uptake of tumor DNA activates the cGAS–STING signal and induces the production of IFN‐I and cytokines (such as IL‐12), as well as the expression of costimulatory molecules (such as CD40, CD80, and CD86)." (PMID 38525112, 2024). "Considering the cis-regulation between PD-L1 and CD80/CD86, tumor-intrinsic mechanisms might coregulate the expression of CD58, PD-L1, and CD80/CD86." (PMID 39349829, 2024). "Moreover, IHC staining analysis demonstrated that more CD86+ TAMs, CD8+ T cells and perforin were observed in tumor samples derived from Tnfrsf14-knockdown GL261 and mGSC cells." (PMID 39085878, 2024). "Moreover, TREM2 inhibited macrophage-expressed antigen-presenting molecules MHC-I/II and the coactivators CD80/CD86, suggesting that TREM2 also affects T cell-mediated anti-tumor immune response." (PMID 39135069, 2024). "In this study, we observed that neither CD68+CD86+SHP2+ TAMs nor CD68+CD206+SHP2+ TAMs in tumor region were indicative of prognosis within the patient cohort." (PMID 38799432, 2024). "The results of flow cytometry showed that the supernatant of tumor cells stimulated by the CaO2 and CaO2‐HSA group could activate dendritic cells to the greatest extent, resulting in increased expression of CD80, CD86, and MHC II." (PMID 38973195, 2024).
tumor (continued). "Treatment with MCP led to an increase in CD86 expression and TNF-α secretion, indicative of enhanced M1 polarization, while reducing CD206 and CD163 expression along with IL-10 secretion, thus supporting a shift towards a more anti-tumor immune response." (PMID 39593969, 2024). "Upregulation in both irradiated and non-irradiated (abscopal) tumor was found when all three co-stimulatory molecules were stained together (CD70+ CD83+ CD86+ DCs)." (PMID 38646638, 2024). "The killing effect of BCR and some costimulatory molecules, such as CD40 and CD86, on the surface of B cells in response to external antigen stimulation or enhancement of costimulatory signals of CD4+ T cells in tumours can also be used as markers for clinical prognostic monitoring." (PMID 36890557, 2023). "The results demonstrated that mPEG-Pep-IDOi/ICG could enhance killing efficacy through CCK-8 assay, induce ICD of tumor cells and upregulate CD80 and CD86, sustaining the DC maturation." (PMID 37238966, 2023). "Indeed, it has been shown that dendritic cells (DCs) that engulf tumor cells treated with recombinant TcCalr mature —represented by an increased expression of MHC II class molecules, CD80, and CD86, among other markers— in a dual canine tumor model." (PMID 36993959, 2023). "CTLA-4 is another popular inhibitory immune checkpoint that could competitively bind CD80 and CD86 against CD28, interrupting the activation of anti-tumor immunity." (PMID 37305457, 2023). "In addition, the supernatant of hypofractionated irradiated tumor cells elevated the percentage of migrating DCs and raised the activation markers CD80 and CD86 expression." (PMID 37833255, 2023). "Finally, to investigate a potential transactivation of CAR T cells by tumor cells, we checked the expression of co-stimulatory ligands, such as CD70, 41BBL, CD80, and CD86, on BxPC-3 tumor cells by flow cytometry." (PMID 37287982, 2023). "Furthermore, myeloid cells possibly suppress anti-tumor responses by secretion of IL10 and interaction via CD80/CD86 with CTLA-4 on reactive CD8+ T cells." (PMID 36761972, 2023). "In vivo studies revealed that ILC1s indeed inhibited tumor growth and upregulated the percentage of macrophage CD86 expression level, while ILC1-blocking antibodies promoted tumor growth in MC38 tumor-bearing mice and decreased macrophage CD86 expression level." (PMID 37679802, 2023). "Next, we measured the CD68, CD86 (M1 marker) and CD163 protein levels in tumor tissues." (PMID 37875398, 2023). "Among the cell populations that were not impacted by the tumor volume, we observed significant enrichment of activated dendritic cells and macrophages (CD86+MHCII+) in tumors from IRAK3-KO mice." (PMID 36757800, 2023). "LRP1B expression in TCs stimulates the infiltration of CD4+ and CD8+ T cells and raises the ratio of CD86/CD163, which may be due to an increase in tumor immunogenicity to achieve immune activation and prevent disease progression." (PMID 38136305, 2023). "In the MOC1 mouse tumor model, metformin combined with a TMVs tumor vaccine significantly increases the expression of CD86 and MHC-II activation markers in TAMs but without a reduction in PD-L1 expression." (PMID 37686159, 2023). "Consistently, moDCs phagocytosed more DOX@3D-MPs-treated tumor cells compared with PBS-treated group, leading to their efficient maturation as indicated by the elevated percentages of costimulatory molecules CD80+ and CD86+ cells in moDCs." (PMID 37875473, 2023). "Immunofluorescence staining revealed a significant reduction on ∼4.5‐fold in CD206+ M2 phenotype macrophages and an increase on ∼4‐fold in CD86+ M1 phenotype after fusion HAC NVs treatment compared with blank NVs, suggesting a down‐regulation of tumour immunosuppression." (PMID 37974395, 2023). "Furthermore, the combination of OX40L with CD80 or CD86, or OX40L with IL-12 dramatically increased both survival and tumor growth delay." (PMID 36839944, 2023).
tumor (continued). "They all have their own ligand on APC (such as CD80, CD86 for CTLA-4 or PD-L1 and PD-L2 for PD-1), and tumor cells, depending on tumor types, may substitute them, thus using this immune checkpoint machinery to avoid cell killing." (PMID 37370768, 2023). "Furthermore, increased DC expression of costimulatory CD80/CD86 was observed in the TME, consistent with the substantial increase in the tumor CD8+ T cells in SAProsome-3–treated mice." (PMID 37524727, 2023). "On the other hand, in early non-small-cell lung cancer (NSCLC), neutrophils which express OX40 ligand, CD86 and 4-1BB ligand could assist the activation of CD4+ T cells to defense tumor cells." (PMID 36934105, 2023). "Furthermore, the immunofluorescence assay of tumor tissues was measured to demonstrate the expression of the M2-phenotype marker (CD206, VEGF, MMP-9), and M1-phenotype marker (CD86)." (PMID 36759928, 2023). "Regarding in vivo tests, TLipIT/NEs under laser irradiation had the best local tumor suppression, the CD80+ and CD86+ mature DCs frequency was ≈33%, significantly higher than the ≈ 16% measured without NIR irradiation, and the ≈11% registered when PBS only was used." (PMID 37238966, 2023). "Furthermore, MC38‐tumor‐infiltrating cDC1 also showed upregulated CD40, CD80, CD86, and MHC‐II expression after RA and anti‐PD‐1 combination treatment." (PMID 36876644, 2023). "Noticeably, several immune checkpoints were significantly overexpressed in the S-AOIs as compared to E-AOIs, such as the T-cell-specific inhibitory receptor HAVCR2 and its corresponding tumor ligand LGALS9, or the inhibitory CD86 that interacts with CTLA4 on T-cells." (PMID 37460925, 2023). "To activate the adaptive immune response to tumors, we detected the expression of CD11c, MHC II, CD86, CD4, CD8, and CD69 in mouse transplanted tumors by IHC and studied the infiltration and activation of DCs and CD4+ T, and CD8+ T cells in the tumor microenvironment after (−)-Guaiol intervention." (PMID 36441354, 2023). "After analysis, PD-L1, CD86, and CD206 were considered to be overexpressed in tumor tissues." (PMID 37306737, 2023). "In addition, the correlation between CD86 and the immune characteristics of different ICB response subgroups, including immune regulators, tumor-infiltrating immune cell-effector genes, immune checkpoints, and immunotherapy-related genes was examined." (PMID 37064861, 2023). "T cell co-stimulation via CD28-CD80/CD86 interactions is required to observe the effects of anti-PD-1 therapies, and we observed little to no expression of these molecules on the tumor cells used (data not shown)." (PMID 35141398, 2022). "Therefore, this nanoplatform dramatically reversed CD206+F4/80+CD11b+ TAMs to CD86+F4/80+CD11b+ M1 phenotype, decreased immunosuppressive FOXP3+CD4+CD25+ Treg cells, and increased anti‐tumor IFN‐γ+CD8+ T cells in B16F10 and 4T1 tumor‐bearing mice." (PMID 37323705, 2022). "Moreover, the M1 macrophage marker CD86 and the M2 macrophage marker molecule CD206 in the MDA-MB-231 xenograft tumour were higher than those in the 231/si xenograft tumour." (PMID 35453742, 2022). "The findings showed that the number of mature CD86+ CD11c+ DCs increased in the draining lymph nodes from 6.05% for blank mice and 10.8% for untreated tumor-bearing mice to 16.5% for PECT-Cur NPs-treated tumor-bearing mice." (PMID 36010836, 2022). "These tolerogenic DCs present tumor antigen without proper costimulation (CD80/CD86), express inhibitory molecules (PDL1/CTLA4), and secrete immunosuppressive factors (TGF-β, IL-10, IL-27, NO, Arg, and IDO)." (PMID 35972798, 2022). "Treatment with OV-mOX40L/IL12 alone or in combination with autologous TIL therapy increased the expression of MHC I, MHC II, costimulatory ligands (CD86 and OX40L), and IL12 in a substantial percentage of the tumor cells, indicating the successful conversion of tumor cells into APC-like cells." (PMID 35715953, 2022).